YAP1 (Yes1 associated transcriptional regulator)
Diseases named in the same sentence as YAP1 in open-access papers (continued):
Sharing a sentence is not in itself a finding about the gene and the disease.
tumor (continued). "YAP1 was expressed in all tumours including the smallest lesions observed in younger animals." (PMID 32404936, 2020). "Furthermore, in the IHC assay of tumour tissues, the expression of YAP1 and COX2 proteins was significantly higher in the GC + CC group compared with that in the GG group." (PMID 32596945, 2020). "However, we repeated our experiments in YAP1‐deficient MKN‐45 cells and found that, in these cells, AGK only mildly regulated tumour cell proliferation." (PMID 32827244, 2020). "Notably, we observed that YAP1 suppression blocked tumour growth, suggesting that proliferation in vivo occurs in cells with higher YAP1 activity." (PMID 31959902, 2020). "In addition, YAP1 is highly associated with HCC and PTC and frequently upregulated during tumor formation." (PMID 32728069, 2020). "Finally, mechanistic studies in vitro and in vivo demonstrated that YAP1 inhibition or NF2 reconstitution impaired tumour growth and proliferation." (PMID 31959902, 2020). "Dysregulated expression of YAP1 has been reported to promote tumor progression." (PMID 30934860, 2019). "Studies also found adaptive reactivation of signal transducer and activator of transcription 3 (STAT3) within the minimal residual surviving drug persister tumor cells, which was co-activated with the SRC-YES-associated protein 1 (YAP1) pathway in EGFR-mutant NSCLC." (PMID 31815659, 2019). "In sum, FLVCR1-AS1 knockdown suppressed tumor growth through miR-513/YAP1 signaling in vivo and FLVCR1-AS1 might be an oncogene in OSC cells." (PMID 31412903, 2019). "Herein, we verified the tumor‐promoting effect of YAP1 in vitro, in vivo, and in human specimens." (PMID 31145543, 2019). "To study whether combined inhibition of PVT1 and YAP1 has stronger anti-tumor activity in EAC, we conducted in vitro and in vivo experiments using PVT1 and YAP1 specific ASOs." (PMID 31601234, 2019). "Our data showed that the ASOs, specific to PVT1 or YAP1, could achieve significant anti-tumor effect in vitro and in vivo." (PMID 31601234, 2019). "Interestingly, the overexpression of both IAP and YAP-1 genes was reported to exert a synergistic effect in promoting tumor-genesis." (PMID 31766357, 2019). "O-GlcNAcylation has been recognized as a major type of post-translational modification, which functions to sense nutrient availability and regulate key oncoproteins, such as Nuclear Factor Kappa B (NF-κB) and Yes-associated protein 1 (YAP1), to support tumor growth." (PMID 31569510, 2019). "To verify the effect of YAP1 inhibition on MLS growth in vivo, we deposited MLS 402‐91 and MLS 1765‐92 cells transduced with two different shRNAs targeting YAP1 on the surface of chicken CAM and observed that YAP1 knockdown significantly impaired their tumor‐forming capacity." (PMID 30898787, 2019). "Hippo/YAP1 pathway was firstly discovered through gene screen of tumor suppressors in Drosophila." (PMID 31613226, 2019). "However, the tumor relapsed in 70% of the mice in approximately two months with a more aggressive phenotype, and these K-Ras-relapsed tumors showed amplification of YAP1." (PMID 31100813, 2019). "Additionally, previous reports have suggested that the tumor suppressive potential of YAP1 is due to its binding to TP73 and its regulation by RASSF1A leading to the expression of pro-apoptotic genes like BBC3/PUMA and BAX." (PMID 30744076, 2019). "However, in other studies, where p73-mediated cell apoptosis was recognized, YAP1 functioned as a tumor suppressor in response to DNA damage." (PMID 31613226, 2019). "Accumulating data suport roles for Yap1 in tumor progression and chemoresistance." (PMID 30956771, 2019). "For instance, within the Hippo signaling pathway, which allows cellular control of organ size and tumor suppression, Yap1 could be targeted in the cytoplasm in cells treated with Nano miR-200c, leading to cell degradation." (PMID 30744585, 2019).
tumor (continued). "When analyzed by YAP1 staining location, total YAP1 expression and nuclear YAP1 expression showed great significance with dismal prognosis in tumor patients (YAP1 expression: HR= 1.90, 95%CI: 1.54-2.33, p<0.001; nuclear YAP1 expression: HR=1.63, 95%CI: 1.29-2.07, p<0.001)." (PMID 31613226, 2019). "YAP1 is a transcriptional coactivator that specifically binds to the transcription factors of oncogenes or tumor suppressor genes, thereby exerting cancer-promoting or tumor-suppressing effects." (PMID 31179326, 2019). "Hence, apart from cytoplasmic phosphorylation and degradation, YAP1 also exerts anti-tumor effect by inducing apoptosis, which is Hippo pathway independent." (PMID 30934860, 2019). "Furthermore, we demonstrated, for the first time, that there is mutual regulation of PVT1 and YAP1 in EAC cells and that co-suppression of PVT1 and YAP1 by their specific ASO led to more effective suppression of EAC tumor growth in vitro and in vivo." (PMID 31601234, 2019). "Increased YAP1 promotes resistance to RAF (Raf-1 proto-oncogene) or mitogen-activated protein kinase kinases inhibitor therapy through transcription active of an anti-apoptotic protein BCL2 like 1 in many types of tumor cells." (PMID 31175271, 2019). "As the nuclear effector of the Hippo pathway, Yap1 plays an important role in many tumor entities." (PMID 31455378, 2019). "YAP1 fusion was detected via FISH in only one grade III tumor (EP117, 1/29, 3.4%)." (PMID 30514397, 2018). "YAP1 protein immunoreactivity was found in both ccRCC tumor and normal kidney sections." (PMID 29850494, 2018). "Here, we investigated the expression and the mechanistic links that could explain the extraordinary potency of YAP1 in driving tumor metastasis, and we show a direct effect of YAP1 on Slug transcription." (PMID 29700328, 2018). "We next investigated whether the tumor-suppressive function of miR-375 is mediated by YAP1 inhibition." (PMID 30514309, 2018). "We evaluated the impact of YAP1 downregulation in vivo in a tumor xenograft model." (PMID 29985391, 2018). "Finally, YAP1, a major downstream effector of the Hippo pathway, has an important role in tumor growth." (PMID 30420728, 2018). "Interestingly, aPKC-ι also regulates YAP1 nuclear localization and activates the Hh signaling pathway to promote tumor growth." (PMID 30389910, 2018). "Moreover, verteporfin treatment was also shown to suppress YAP1 activity along with the viability, invasion, and tumor sphere formation of MM cell lines in vitro." (PMID 29565815, 2018). "Suh revealed that YAP1 had a tumor suppressor function in GC." (PMID 30539010, 2018). "Typically in quiescent cells, Yap1 is phosphorylated downstream of the tumor suppressive Hippo pathway, by Lats1 and Lats2 kinases; phosphorylation leads to its sequestration in the cytoplasm by 14–3-3 proteins resulting in proteasomal degradation, thereby preventing its nuclear import." (PMID 30322398, 2018). "The transcription factors YAP and TAZ (encoded by YAP1 and WWTR1 genes, respectively) that are normally restricted by the conserved Hippo tumor-suppressor pathway, are activated in diverse cancers and are increasingly associated with nuclear sensors for biomechanical signals." (PMID 29415512, 2018). "To demonstrate that YAP1 suppresses UPR in vivo we stained tumor sections from allografts expressing control (scr) and Rela shRNA as well as our KP, KPY, and SAHA/JQ1-treated KP tumors for the UPR target Gadd34 and found that it was upregulated in Yap1/NF-κB-deficient tumors." (PMID 30382078, 2018). "LIFR was found to promote membrane localisation factor Scribble which in turn led to the activation of Hippo signalling and phosphorylation and functional inactivation of the transcriptional co-activator Yes-associated protein 1 (YAP1) and subsequent suppression of tumour metastasis." (PMID 30263091, 2018). "YAP1/TAZ function in tumour cell proliferation, survival, metastasis and stemness." (PMID 28782275, 2018).
tumor (continued). "The precise tumor-related function of some YAP1 targets is still under investigation and may depend on expression levels, cell origin and/or the genetic and epigenetic background." (PMID 29179447, 2017). "miR-16, as a novel tumor suppressor in CCA through directly targeting YAP1, might be a promising therapeutic target or prognosis biomarker for CCA." (PMID 28915618, 2017). "Lymph node metastases from orthotopic xenografts express YAP1 more strongly than primary tumours." (PMID 28098159, 2017). "Interestingly, previous report indicated that oncogenic Kras, YAP1, and β-catenin serve similar functions in cell cycle control in tumor initiation." (PMID 28241877, 2017). "Moreover, in mouse models of PCa, YAP1 can also regulate the recruitment of polymorphonuclear myeloid-derived suppressor cells, which promotes tumor growth." (PMID 29383141, 2017). "In the present study, we have declared that YAP1 may act as a tumor inducer by stimulating the ERK/MAPK signaling pathway in PTC." (PMID 28036290, 2017). "Because both YAP1 and HSPC111 are linked to c-Myc, we hypothesized that they could be valuable biomarkers of tumor progression, and that the YAP1 and HSPC111 co-expression status might hold significance for GC." (PMID 29113304, 2017). "In addition, loss of YAP1 expression leads to reduced ECS cell survival and inhibition of YAP1 function reduces tumor formation." (PMID 29088716, 2017). "In support of the point that epithelial-mesenchymal transition (EMT) is closely associated with metastasis of tumor cells, we found that in small LoVo cells not large cells, knockdown of YAP1 down-regulated the expression of vimentin, a key EMT protein." (PMID 29296212, 2017). "YAP1, an effector of the Hippo signaling pathway, has been reported to be an oncogene that stimulates proliferation, tumorigenicity and metastasis in several tumor types." (PMID 28036290, 2017). "Given our previous findings that nuclear YAP1 expression is enriched in basal cells, we hypothesized that YAP1 may contribute to tumor growth through modulation of PCa progenitor-like cells." (PMID 29383141, 2017). "YAP1 was unmethylated in the tumor as well as the normal samples." (PMID 29179447, 2017). "Transcriptional co-activators Yes-Associated Protein 1 (YAP1) and transcriptional coactivator with PDZ-binding motif (TAZ) mediate the activity of the Hippo signaling pathway in control of cell proliferation and in tumor progression." (PMID 28061504, 2017). "Likewise, many studies supported the role of the nuclear transcription factor yes-associated protein 1 (YAP1) in compensating cancer cell survival and proliferation in KRAS-independent neoplasms, including PDAC." (PMID 28895920, 2017). "The role of YAP1 in cancer remains controversial and conflicting reports on whether YAP1 functions as a tumor suppressor or as an oncogene have been reported in literature." (PMID 29228705, 2017). "A subcutaneous tumor xenograft model was used to further demonstrate whether YAP1 is required for tumor growth in vivo." (PMID 29163769, 2017). "We found that YAP1 silencing led to impairment of cellular proliferation and tumor cell migration." (PMID 29228705, 2017). "Conversely, majority of the HN137-Met tumour displayed uniformly high levels of YAP1." (PMID 28874669, 2017). "Finally, immunohistochemical analysis for xenografts tumor tissues showed that ivermectin-treated xenografts displayed weaker YAP1 and Ki67 staining than control mice." (PMID 29296196, 2017). "Importantly, evaluation of a biopsy of the dermal lesion by IHC with YAP1 antibody revealed that the persistent gefitinib-resistant tumour was indeed positive for YAP1 expression." (PMID 28874669, 2017). "Indeed, this was demonstrated when patient HN137, who initially responded to gefitinib treatment, developed treatment failure, and as predicted, the resistant tumours were uniformly YAP1 positive." (PMID 28874669, 2017).
tumor (continued). "Besides interacting with TCF/LEF, β-catenin also binds to p300/CBP, TATA-box binding protein (TBP), Pontin52, Reptin52, Brg-1, MUC1-C, SOX10, p68/p72, FOXM1, yes-associated protein 1 (YAP1) and FBW1, which are all involved in tumor development or progression." (PMID 28430641, 2017). "In addition, studies have shown that VEGF-C increases YAP1, down-regulates the expression of slug, and thus enhances the self-renewing capacity and metastatic potential of tumor cells." (PMID 29296212, 2017). "In conclusion, we for the first time discovered that that miR-16, as a tumor suppressor in CCA via targeting YAP1, may serve as a promising therapeutic target for CCA." (PMID 28915618, 2017). "The low YAP1 mRNA expression group (n = 35) had a lower frequency of tissues showing poorly differentiated histology (P < 0.05), less tumor invasion (P < 0.05), and lower rates of venous invasion (P < 0.05) compared with the high expression group (n = 66) in the Kyushu dataset." (PMID 29296196, 2017). "Two methods–immunofluorescence and immunoblotting–were used for the detection of four molecular markers (β-catenin, filamin A, GAB1 and YAP1) in patient-derived cell lines to compare the results with those obtained from the corresponding tumor samples on the protein level." (PMID 28231263, 2017). "A YAP1 target gene that displays a tumor suppressive effect is ANKRD1." (PMID 29179447, 2017). "Additionally, the only two tumor growths originating from Yap1-ko cells contained approximately 80 % GFP−tdTomato+ cells harboring a functional Yap1 gene." (PMID 26695440, 2016). "Therefore, the actual TIC frequency within Yap1-ko tumor cells should be even lower than we detected here." (PMID 26695440, 2016). "Noteworthy, emerging data showed that YAP1 is negatively regulated by miR-141, miR-375 and miR-181c, which serves an independent prognostic factor for PC patients and functions as tumor suppressors." (PMID 27738325, 2016). "Patient outcome is further worsened if Nodal and YAP1 are both expressed in the same tumor." (PMID 27325246, 2016). "Results showed that silencing YAP1 significantly inhibited tumor growth." (PMID 27835600, 2016). "Furthermore, a previous study demonstrated that α-catenin is a tumor suppressor that inhibits YAP1 activity and that YAP 1 is a key driver of keratinocyte proliferation induced by α-catenin loss." (PMID 27835600, 2016). "Finally, the present study is the first to report that silencing YAP1 in BGC-823 GC cells significantly suppressed hematogenous metastatic spread of tumor cells." (PMID 27835600, 2016). "This increased expression in cancer suggests that Nodal and YAP1 might play important roles in tumor proliferation, angiogenesis, invasion, and metastasis." (PMID 27325246, 2016). "As a transcriptional coactivator, Yap1 could upregulate or downregulate downstream genes in different tumor types or in different phases of tumor development." (PMID 26695440, 2016). "In contrast to RAF1, YAP1 protein levels were higher in tumours compared with the surrounding tissue, and the degree of YAP1 expression in tumours (ratio of YAP1 expression in matched tumour/non-tumour tissue) positively correlated with tumour grade." (PMID 28000790, 2016). "Thus, MST1/2 and LATS1/2 would be tumour suppressors that negatively regulate by direct phosphorylation YAP1, which would behave as an oncogene." (PMID 27322327, 2016). "Lastly, we tested whether the increase of the TIC fraction was consistent with tumor initiating ability in vivo in Yap1 active tumors." (PMID 26695440, 2016).
tumor (continued). "However, this original contamination of ∼2 % GFP− cells expanded to final ∼80 % GFP− cells within resulting tumors over one month of growth in vivo, suggesting a greater growth advantage of tumor cells with intact Yap1 than cells with Yap1 deletion." (PMID 26695440, 2016). "Furthermore, transcriptome analysis showed that YAP1 transfection in Huh7 cells induces over-expression of genes involved in tumor stemness." (PMID 27359056, 2016). "We found that YAP1 KO displayed impaired sphere formation and reduced tumour-initiating capacity." (PMID 27905400, 2016). "YAP1 is functionally associated with the ECM through its non-canonical, Hippo-independent role as a mechanotransducer, and, as a central effector in mechanotransduction, YAP1 influences how tumor cells sense and respond to the mechanical properties of the ECM and to their microenvironment." (PMID 27036018, 2016). "Thus, Yap1 appears to promote tumor development by not only blocking growth inhibition but also by activating the EMT that is induced by the TGF-β/Smad signaling pathway." (PMID 26695440, 2016). "We next deleted YAP1 gene in HCC primary tumour cells using CRISPR/Cas9 technology." (PMID 27905400, 2016). "Moreover, expression levels of lncBRM together with YAP1 signalling targets are positively correlated with tumour severity of HCC patients." (PMID 27905400, 2016). "Nevertheless, additional study is necessary to further address the potential role of YAP1 in migration/invasion in vivo, since there is a possibility that reduced tumor expansion in the lung was due to YAP1 role in inhibiting the cell cycle that contributed to the observation." (PMID 27835600, 2016). "Although cytoplasmic Yap1 could be detected in all tumor cells, strong nuclear expression of Yap1 was detected specifically in Krt14-positive TICs." (PMID 26695440, 2016). "In addition, the ratio of RAF1/YAP1 expression in the same tumour negatively correlated with histological grade in the whole cohort, indicating that tumours with low RAF1, high YAP1 protein levels are found in the most malignant group." (PMID 28000790, 2016). "Collectively, we report NDR1/2 as physiological YAP1-S127 kinases that might function as tumor suppressors upstream of YAP1 in human colorectal cancer." (PMID 25601544, 2015). "Moreover a separate experiment investigating short term effects on xenografts following drug treatment showed induction of BIM mRNA and a reduction of YAP1 mRNA expression in combination-treated tumor tissue xenografts." (PMID 26087189, 2015). "In CRC tissues, YAP1 expression was mainly observed in the nuclear of tumor cells." (PMID 25473897, 2015). "Finally we identify a set of YAP1 targets genes by expression profiling following YAP1 knockdown representing a gene signature that can predict YAP1 activity in tumor samples." (PMID 26295846, 2015). "Although the tumor-promoting function of YAP1 and TEAD by controlling a remarkable range of cellular processes is undisputed, the comprehensive ensemble of direct downstream target genes and the underlying mechanisms of target gene regulation remain poorly understood." (PMID 26295846, 2015). "In conclusion, targeting YAP1 by tumor suppressor miRNA miR-15a and miR-16-1 plays inhibitory effect and this might have a therapeutic potential in GAC." (PMID 25743273, 2015). "Nonetheless, amplification of CCND1 was not a prerequisite for YAP1 gene loss, as there were several tumours with low YAP1 copy number where increased CCND1 copy numbers were not present." (PMID 24559095, 2014). "In our study, YAP1 expression was not informative of outcome in the untreated ER+ subgroup of the randomised cohort which might be expected if YAP1 had had true tumour suppressive properties." (PMID 24559095, 2014). "Moreover we detect YAP1 copy number amplification in clinical series of different human tumor types and identify the downstream genes and pathways that are critical as YAP1 effectors in carcinogenesis." (PMID 24810989, 2014).